ETV6 (ETS variant transcription factor 6)
Diseases named in the same sentence as ETV6 in open-access papers (continued):
Sharing a sentence is not in itself a finding about the gene and the disease.
Thrombocytopenia (continued). "Conditional knockout of Etv6 in megakaryocyte (MK) erythroid progenitor cells in mice results in thrombocytopenia, with an increased frequency of MK colony-forming cells." (PMID 32841218, 2020). "Collectively, these data suggest that ETV6 is required for homeostatic transcriptional control in MKs, and the altered interferon and cytoskeletal gene programs we observed may predispose patients with ETV6 mutations to thrombocytopenia via decreased proplatelet formation." (PMID 32841218, 2020). "Other ITs to consider which may also present with thrombocytopenia with normal platelet size include RUNX1-related thrombocytopenia (RUNX1-RT), ETV6-related thrombocytopenia (ETV6-RT) and CYCS-related thrombocytopenia (CYCS-RT)." (PMID 35587581, 2022). "ETV6-related thrombocytopenia was detected in two patients (1%) (one male and one female)." (PMID 36507135, 2022). "Insofar management for thrombocytopenias associated with RUNX1, ANKRD26, or ETV6 mutations are concerned, a cytogenetic bone marrow examination is recommende at the time of diagnosis, particularly if the mutations have already been reported and have proven pathogenicity." (PMID 33926054, 2021). "The first association between ETV6 germline variation and B-ALL was in 2015 when four studies described carriers of ETV6 variants with a median age of 11 years and clinical features of mild to moderate thrombocytopenia and 30% lifetime risk of hematologic malignancies, particularly B-ALL." (PMID 40925926, 2025). "The majority of ETV6/RUNX1-positive patients had combined moderate anemia and thrombocytopenia at the onset of disease, with a significantly higher proportion than the negative group (55 vs. 49.9%, P< 0.001; 75.0 vs. 70.9%, P= 0.007, respectively)." (PMID 34988026, 2021). "The ETV6-RT phenotype is characterized by a mild form of thrombocytopenia without alteration in platelet function." (PMID 40004441, 2025). "To date, the pathogenetic mechanisms responsible for thrombocytopenia and the neoplastic evolution in ANKRD26-RT, FPD/AML, and ETV6-RT are still unknown." (PMID 39791724, 2024). "Our findings suggest that ETV6 is required for HDAC-mediated effects on MK differentiation, and the exclusion of ETV6 shifts the balance of histone and protein acetylation, resulting in defective proplatelet formation and clinical thrombocytopenia." (PMID 32841218, 2020).
myeloid neoplasm (30 papers, 2017 to 2025). Proliferation of myeloid cells originating from a primitive stem cell. "Other hereditary syndromes involve genes such as ANKRD26 and ETV6, both presenting with autosomal dominant thrombocytopenia and an increased predisposition to myeloid malignancies, including MDS and acute leukemia (AL)." (PMID 40565579, 2025). "Although rare, ETV6 mutations are recurrent somatic events in myeloid neoplasms and are associated with a poor prognosis in MDS." (PMID 40565579, 2025). "Chromosomal translocations involving meningioma 1 (MN1) and ETS variant 6 (ETV6) genes are extremely rare, but recurrent in myeloid neoplasms." (PMID 36975735, 2023). "We present our recent experience in the identification of an ETV6 was associated with hematologic malignancies, in particular myeloid malignancies, and recently described as mutated also in oncologic patients." (PMID 32148977, 2020). "ETV6 was associated with hematologic malignancies, in particular myeloid malignancies, and recently described as mutated also in oncologic patients." (PMID 32148977, 2020). "With the exception of an NF1-RHOT1 fusion that would result in NF1 loss-of-function, the remaining 3 fusions identified (NUP98-KDM5A, DEK-NUP214, ETV6-MECOM) are known to be associated with myeloid malignancies." (PMID 29146900, 2017). "However, there are marked differences in cancer predisposition: the ANKRD26 variant predisposes to myeloid malignancies, ETV6 predominantly predisposes to B-cell ALL, and RUNX1 is associated with myeloid malignancies, and, to a lesser extent, predisposes to T-cell ALL." (PMID 38203823, 2024). "Likely-pathogenic variants were also identified in the ETV6 and DDX41 genes, both of which are key to hematopoiesis in myeloid neoplasms." (PMID 40725152, 2025). "Herein, we describe our case and review the literature to summarize the clinical and laboratory findings in patients with this rare but recurrent MN1::ETV6 gene fusion observed in myeloid neoplasms." (PMID 37434656, 2023). "We characterized genomic alterations in an individual with ETV6::ABL1 gene-fusion-positive myeloid neoplasm using various genomic technologies." (PMID 37895201, 2023). "Among the thirty-one patients, five (16.1%) had causative germline variants predisposing them to myeloid neoplasms in the GATA2, PGM3, and ETV6 genes, and all of these identified variants have been previously reported." (PMID 38137719, 2023). "A subset of patients with familial thrombocytopenia are at increased risk of developing myeloid neoplasms during their life time, particularly those with germline autosomal dominant mutations in the RUNX1, ANKRD26, and ETV6 genes." (PMID 33802366, 2021). "Translocations involving band 12p13 are frequently seen in myeloid malignancies, through which ETV6 is frequently rearranged." (PMID 32723365, 2020). "ACSL6 could be translocated with ETV6 in myeloid neoplasms, and the gene fusion might activate the oncogene near the translocated chromosomes to initiate tumorigenesis." (PMID 38045683, 2023). "Of note, in 2016 the World Health Organization classification included myeloid malignancies arising from germline mutations in ANKRD26, RUNX1, and ETV6 into a new category defined as “Myeloid neoplasms with germline predisposition and pre-existing platelet disorders”." (PMID 33802366, 2021). "KMT2A fusions were the most common (n = 28, 60%, GRIN p = 1.86 × 10−74) and other in-frame fusions previously reported in myeloid malignancies involving NUP98 (n = 3) and ETV6 (n = 2) were also observed." (PMID 33579957, 2021).
myelodysplastic syndrome (20 papers, 2009 to 2025). A clonal hematopoietic disorder characterized by dysplasia and ineffective hematopoiesis in one or more of the hematopoietic cell lines. "It has been demonstrated that ETV6 mutation is a predictor of shortened survival in myelodysplastic syndromes." (PMID 35646048, 2022). "Although the translocations or deletions of ETV6 gene are reported in a variety of hematologic neoplasms, including acute myeloid and lymphoblastic leukemia, myelodysplastic syndrome, and myeloproliferative disorders, it is rarely reported in DLBCL." (PMID 29992138, 2018). "Two cases of ETV6 amplification have been described: one in B lymphoblastic leukemia and the other in myelodysplastic syndrome." (PMID 24886876, 2014). "At present, mutual translocation of MDS1/EVI1 and ETV6 has been observed in only two AML-M4 cases; secondary to myelodysplastic syndrome (MDS) and in CML in blast crisis." (PMID 24527086, 2014). "To analyze specific gene expression patterns of ETV6::RUNX1‐translocated preleukemia in a model without additional secondary alterations, we generated monoclonal hiPSC lines derived from two donors: HW8 and ChiPSC12." (PMID 40177616, 2025). "In patient BMA17, referred for myelodysplastic syndrome, OGM detected a heterozygous 1.4 kb insertion in a 6.6 kb region located between two OGM labels (ogm[GRCh37]ins(12p13.2)(11,889,007_11,895,594)) that includes ETV6 (chr12:11,802,788–12,048,325)." (PMID 38605095, 2024).
breast carcinoma (15 papers, 2008 to 2024). "In external validation datasets, these associations, including deletions in PTEN and LRP1B or amplifications of MYC, CEP89 and ETV6, featured most prominently in the largest cohort of breast cancer samples." (PMID 37221612, 2023). "ETV6 plays a key role in hematological diseases, breast cancer, and salivary gland cancer." (PMID 36914737, 2023). "Studies have reported that CELSR2, ETV6, MGAT1, and RFX5 were associated with breast cancer." (PMID 35071020, 2021). "It has been suggested that ETV6 knockdown could inhibit migration and invasion abilities of breast cancer Hs578T cells." (PMID 32326970, 2020). "For example, a fusion of ETV6 (ETS translocation variant 6) to TRKC leads to the constitutive activation of TRKC tyrosine kinase, which promotes tumor formation and progression in human breast carcinoma." (PMID 23874207, 2013). "Prior to IFNγ stimulation, the TFs demonstrating the highest connectivity were dominated by TFs previously identified for regulating facets of breast cancer biology (in black), including SOX9, GATA3, and ETV6." (PMID 35902886, 2022).
eosinophilia (15 papers, 2009 to 2026). "The ETV6 gene, located at 12p13, belongs to a large family of transcription factors and has been previously implicated in the pathogenesis of multiple hematological malignancies, occasionally related with eosinophilia." (PMID 23710385, 2013). "The ETV6::ABL1 fusion was recently included in the genetic abnormalities defining the disease category of myeloid/lymphoid neoplasms with eosinophilia and tyrosine kinase gene fusions (MLN-TK)." (PMID 39066837, 2024). "The ETV6::ABL1 fusion defines a subgroup of myeloid/lymphoid neoplasms with eosinophilia and tyrosine kinase gene fusions." (PMID 39066837, 2024). "Eosinophilia, a morphological hallmark of MLN-TK with ETV6::ABL1, persisted throughout the disease progression in our case, from the MPN phase to the 1st blast phase." (PMID 39066837, 2024). "At present, the reported cases of MDS, MPN and CML with ETV6 gene positive showed varying degrees of eosinophilia, and some patients were effective in TKI treatment." (PMID 39634885, 2024). "ETV6-LYN gene fusion caused by the remodelling between chromosomes 8 and 12 may lead to MPN and T-lymphoblastic lymphoma associated with eosinophilia, while it was included in the eosinophilia and other gene fusion categories by the World Health Organisation." (PMID 28958974, 2018). "This category name has changed from the previous “myeloid/lymphoid neoplasms with eosinophilia and rearrangement of PDGFRA, PDGFRB or FGFR1, or with PCM1::JAK2” (MLN-eo), to specify the underlying molecular genetic changes and to include cases with ETV6::ABL1, FLT3 fusions or other TK fusion genes." (PMID 37454239, 2023). "In one case who entered remission after the treatment of eosinophilia and associated T-lymphoblastic lymphoma and recurrent eosinophilia, complex translocations between chromosomes 7, 12 and 16 were detected, while FISH analysis revealed that the ETV6 gene (12p13) was responsible for the clonality." (PMID 28958974, 2018). "Comprehensive evaluation revealed persistent marked eosinophilia (peak 15,000/μL), prompting hematological investigation, including a bone marrow biopsy and cytogenetic analysis that confirmed CEL harboring the ETV6-SYK fusion oncogene." (PMID 42005114, 2026). "Previous studies have also shown the presence of eosinophilia in all MPN and AML cases with ETV6::ABL1." (PMID 39066837, 2024). "The MLN-TK with ETV6::ABL1 shares common clinicopathological features with chronic myeloid leukemia, such as eosinophilia and response to tyrosine kinase inhibitor (TKI) therapy, due to the structural and functional similarity of the fusion proteins." (PMID 39066837, 2024). "Blastic transformation is usually myeloid, and several de novo cases of AML with ETV6-PDGFRB and eosinophilia have also been reported." (PMID 38337573, 2024). "Myeloid or lymphoid neoplasms with eosinophilia can demonstrate gene rearrangements in PDGFRA, PDGFRB, FGFR1, JAK2, or FLT3 or ETV6::ABL or other tyrosine kinase gene fusion (MLN-TK)." (PMID 38611061, 2024). "In the case of eosinophilia, FISH/cytogenetics and molecular analysis (on bone marrow aspirate or peripheral blood cells) should specifically look for PDGFRA, PDGFRB, FGFR1, FLT3, ETV6, and JAK2 gene rearrangements." (PMID 37274287, 2023). "FIP1L1::PDGFRA and ETV6::ABL1 fusion genes share striking clinical and morphological similarities including male predominance, the relative frequency of eosinophilia and monocytosis, the median absolute number of eosinophils, and presentation or progression to BP including EMD." (PMID 37454239, 2023). "Therefore, an RNA-based study capable of sensitively detecting ETV6::ABL1 should be used for diagnostic evaluation, especially in patients with MPN featuring eosinophilia and lacking the BCR::ABL1, considering clonal burden and disease phenotype in the interpretation of results." (PMID 39066837, 2024).
eosinophilia (continued). "Eosinophilia is present in almost all cases of MLN-TK, caused by fusion genes involving a receptor [PDGFRA or B, fibroblast growth factor receptor (FGFR), fms like tyrosine kinase 3 (FLT3)], a transcription factor (ETV-6), or a non-receptor kinase (Janus kinase 2, JAK2)." (PMID 37274287, 2023). "In 81/135 (60%) evaluable patients, hypereosinophilia (>1.5 × 109/l) was observed in 40/44 (91%) FIP1L1::PDGFRA and 7/7 (100%) ETV6::ABL1 positive patients but only in 13/30 (43%) patients with PDGFRB, FGFR1, and JAK2 fusion genes while 9/30 (30%) patients had no eosinophilia." (PMID 37454239, 2023).
B-cell acute lymphoblastic leukemia (13 papers, 2011 to 2025). A neoplasm of lymphoblasts committed to the B-cell lineage, typically composed of small to medium-sized blast cells. "For example, ETV6 (also known as TEL) are occasionally fused with RUNX1 (also known as AML1) in childhood precursor B-cell acute lymphoblastic leukemia." (PMID 21789226, 2011). "In B cell acute lymphoblastic leukemia (B-ALL), a number of PAX5 fusion proteins have been reported, including PAX5::ETV6, a fusion of the paired domain from PAX5 to a large portion of the ETV6 protein, which includes its helix-loop-helix and ETS domains." (PMID 38473380, 2024).
fibrosarcoma (13 papers, 2020 to 2026). A malignant mesenchymal fibroblastic neoplasm affecting the soft tissue and bone. "The NTRK fusions include translocated promoter region (TPR)-NTRK1 in thyroid cancer, tripartite motif containing 24 (TRIM24)-NTRK2 and ETS variant transcription factor 6 (ETV6)-NTRK3 in fibrosarcoma." (PMID 34209967, 2021). "While ETV6::NTRK3 is a well-established genetic driver of infantile fibrosarcoma, other fusions of NTRK1/3 and various other kinase genes including MET, RET, RAF1, or BRAF have been implicated in the pathogenesis of these tumors." (PMID 38217715, 2024). "Among them, tumors resembling lipofibromatosis or malignant peripheral nerve sheath tumors often harbor intra-chromosomal NTRK1 rearrangements, while most infantile fibrosarcomas are characterized by canonical ETV6::NTRK3 fusions." (PMID 36801905, 2023). "The ETV6::NTRK3 fusion represents the canonical fusion (90% frequency) for both infantile fibrosarcoma and mammary analog secretory carcinoma, while being detected at a much lower frequency (5–10%) in a variety of other cancers of various lineages." (PMID 36801905, 2023). "While ETV6- NTRK3 fusion is common in infantile fibrosarcoma, NTRK1/3 fusion in pediatric tumors is scarce and, consequently, not well known." (PMID 32957984, 2020). "Infantile Fibrosarcoma is a malignant tumor of fibroblastic origin, typically found in early childhood, locally aggressive, and characterized by molecular alterations that activate tyrosine kinase signaling, primarily the ETV6::NTRK3 fusion." (PMID 39940949, 2025). "FISH detection of ETV6::NTRK3 is sufficient to confirm the diagnosis of infantile fibrosarcoma." (PMID 38217715, 2024). "In detecting ETV6-NTRK3 fusions, a widely used commercial probe is the isolated ETV6 probe, effectively confirming ETV6-NTRK3 rearrangements in infantile fibrosarcomas." (PMID 37920823, 2023). "ETV6::NTRK3 fusion has been identified in not only infantile mesenchymal neoplasms, such as infantile fibrosarcoma/congenital “cellular” mesoblastic nephroma and secretory carcinomas of the breast, salivary gland, skin, but also in thyroid cancers associated with a history of radiation." (PMID 38390852, 2024). "One of the typical pediatric tumors, Infantile Fibrosarcoma (IFS), is a malignant tumor of fibroblastic origin, typically found in early childhood, locally very aggressive, and characterized by molecular alterations that activate tyrosine kinase signaling, primarily the ETV6::NTRK3 fusion." (PMID 39940949, 2025). "Similarly, EGFR ITDs are described in the setting of infantile fibrosarcoma and congenital mesoblastic nephroma, particularly in classic or mixed subtype, and aids in diagnostics if the tumor is negative for the more commonly identified ETV6::NTRK3 fusion." (PMID 37686670, 2023). "The negativity of ETV6 and NTRK1 excludes the possibility of infantile fibrosarcoma." (PMID 40522461, 2025).